MDM4 (MDM4 regulator of p53)
Diseases named in the same sentence as MDM4 in open-access papers (continued):
Sharing a sentence is not in itself a finding about the gene and the disease.
breast carcinoma (continued). "Elevated expression of MDM4 has been seen in both relatively rare (e.g., retinoblastoma and ocular melanoma) and more common (e.g., cutaneous melanoma and breast cancer) types of tumor." (PMID 27738340, 2016). "To determine if protein complexes consisting of ERα and MDM4 were relevant in vivo, we conducted a co-IP experiment using lysate from an ERα-positive, treatment-naive, primary breast carcinoma patient tissue sample." (PMID 26909605, 2016). "Knockdown of MDM4 inhibits the proliferation of breast cancer cells, induces the expression of the cyclin dependent kinase inhibitor CDKN1A/p21waf1/cip1, and causes G1-phase cell cycle arrest and senescence." (PMID 26909605, 2016). "Immunohistochemical analysis of MAGE-A and MDM4 in a cohort of 225 human primary breast cancer specimens." (PMID 26001071, 2015). "Recently, a 4-nitrobenzofuroxan derivative, XI-006 (NSC207895) was shown to diminish MDM4 promoter activity in breast cancer cell lines." (PMID 26095524, 2015). "Given, however, the small proportion of the breast cancers that express detectable MAGE-A protein, this association should be explored in greater depth in cancers where MAGE-A and MDM4 increases are more common." (PMID 26001071, 2015). "We sequenced the whole MDM4 coding region and flanking untranslated regions in genomic DNA samples obtained from 40 German patients with familial breast cancer." (PMID 18279506, 2008). "We thus sequenced all exons and flanking non-coding sequences of MDM4 in 40 German patients with familial breast cancer." (PMID 18279506, 2008). "Survey of genetic alterations of the MDM4 gene identified in 40 patients with familial breast cancer." (PMID 18279506, 2008). "It is the first study, to our knowledge, that assesses the frequency distribution of MDM4 germ-line alterations in familial breast cancer." (PMID 18279506, 2008). "As such, we identified an SDF-1/CXCR4/MDM2/MDM4 signal transduction axis that we speculate participates in driving breast cancer metastasis." (PMID 39766093, 2024). "While the MDM4-AA genotype had an OR = 3.07 (CI = 0.3819–36.8217), RR = 2.22 (0.4048–12.2007), and p = 0.35, indicating that it was not linked to breast cancer susceptibility." (PMID 36831624, 2023). "In contrast, the MDM4-AG genotype had an OR = 0.79 (CI = 0.4559–1.3803), RR = 0.90 (0.7129–1.1463), and p = 0.41, indicating that it was not linked to breast cancer susceptibility." (PMID 36831624, 2023). "The close proximity of NUAK2, which we find is commonly co-amplified with MDM4 in breast cancer, may fortuitously confer a vulnerability to GPX4 inhibition that could be exploited for therapy." (PMID 35523770, 2022). "NUAK2 is amplified along with MDM4 in a subset of breast cancers, particularly the claudin-low subset, suggesting that this may predict vulnerability to GPX4 inhibitors." (PMID 35523770, 2022). "miR-1307 may play a part in the development of resistance for chemotherapy in breast cancer by the modulation of apoptosis and targeting the Mdm4 protein." (PMID 35456388, 2022). "In this study, we confirmed the impact of MDM4 rs4245739 on ER status, and we consider that AA genotype could indicate better breast cancer prognosis." (PMID 33669778, 2021). "The information may improve the assessment of prognostic and/or predictive value of MDM2 and MDM4 genotypes in breast cancer patients." (PMID 33669778, 2021).
breast carcinoma (continued). "The evidence suggests that MDM2 and MDM4 may play significant roles in breast cancer formation, progression, prognosis, and protection from cancer." (PMID 33669778, 2021). "Thus, this study aimed to investigate the relationship between SNPs in MDM2 (rs2279744, rs937283, rs937282) and MDM4 (rs1380576, rs4245739) and I–II stage breast cancer." (PMID 33669778, 2021). "It has also been reported that the mdm4/mdm2 heterodimers are upregulated not only in the brain and nerve tumor tissues, breast cancer, soft tissue sarcomas, type 1 diabetes, and systemic lupus erythematosus, but also in the parathyroid glands of patients with renal secondary hyperparathyroidism." (PMID 35070964, 2021). "Actually, MDM4 has been emerging as an important breast cancer biomarker and oncoprotein." (PMID 32802855, 2020). "Intriguingly, MDM4 was significantly overexpressed in the luminal A subtype of breast cancer." (PMID 32802855, 2020). "To note, breast cancer is a tumor with a high incidence of MDM4 overexpression." (PMID 31547268, 2019). "Thus, MDM4 is active in 40% of breast cancers, showing that this gene can be considered a new target for antitumor therapies." (PMID 30104527, 2018). "For this reason, we analysed MDM4 and mTOR in the database of human breast cancer." (PMID 28270148, 2017). "The inverse correlation between MDM4 and mTOR observed in human breast cancer specimens is in agreement with this hypothesis." (PMID 28270148, 2017). "Additionally, the group showed a positive correlation between MAGE-A and MDM4 by immunohistochemistry in primary breast cancer." (PMID 28056866, 2017). "The MDM2 homolog, MDM4, is also overexpressed in human breast cancer." (PMID 26909605, 2016). "Therefore, we conclude that ERα is found in complex with MDM4 in human breast cancer cell lines and in patient breast tumors." (PMID 26909605, 2016). "Moreover, signaling pathways that mediate the overexpression of MDM4 in human breast cancer remain to be elucidated." (PMID 26909605, 2016). "Since MDM4 expression is frequently elevated in luminal breast cancers, and the majority of luminal tumors are ERα-positive, we propose that ERα and MDM4 may be coexpressed with one another in human breast cancer and may regulate each other's expression." (PMID 26909605, 2016). "By doing so, we confirmed the MDM4 SNP34091CC/MDM2 SNP309 GG genotype to associated with reduced risk of breast cancer (OR = 0.47; 95% CI = 0.24–0.92, when compared with the highest risk genotype (MDM4 SNP34091AA/MDM2 SNP309GG), data not shown)." (PMID 26471763, 2015). "Genetic alterations of the MDM4 gene in 40 German patients with familial breast cancer." (PMID 18279506, 2008). "Altogether, this study did not support a major role for MDM4 coding variants in familial breast cancer risk." (PMID 18279506, 2008).
breast carcinoma (continued). "Thus, we selected 2 TF hubs (MDM4 and ZNF410) and 2 lncRNA hubs (AC084219 and CTB-89H12) with the highest degrees from the lncRNA-TF-associated ceRNA network and detected their expression in various subtypes of breast cancer." (PMID 32802855, 2020). "In addition, Several previous studies including genome-wide association study (GAWS) had confirmed the relationship between MDM4 3′-UTR SNPs and susceptibility of breast cancer, esophageal squamous cell carcinoma, and small cell lung cancer in different ethnic populations." (PMID 27462918, 2017). "Therefore, as enthusiasm for the preclinical development of novel MDM4/MDM2 inhibitors builds, we propose that these future agents may show utility in combination with hormonal therapies for the treatment of MDM4/MDM2-driven breast cancers." (PMID 26909605, 2016). "c‐Myc drives the alternative splicing of genes MDM4 and Bcl‐x in breast cancer cells by transcriptionally upregulating serine/arginine‐rich splicing factor 10 (SRSF10), thereby accelerating breast cancer progression." (PMID 40443721, 2025). "An oncogene pathway known to promote breast cancer metastasis in MDA-MB-231 xenografts is that of Mouse Double Minute 2 and 4 (MDM2 and MDM4, also known as MDMX)." (PMID 39766093, 2024). "To further validate the therapeutic potential of MDM4, we conducted study on the small molecule MDM4 inhibitor, NSC146109, in different tumor cell lines (kidney cancer: 786-O; breast cancer: MCF-7; lung cancer: A549; colon cancer: HCT116)." (PMID 38281029, 2024). "High expression of MDM4 and MDM2 occurs frequently in human cancers, including breast cancer, gliomas, soft tissue sarcomas, and melanomas." (PMID 39345743, 2024). "Specifically, ERα can up-regulate the expression of MDM4 and MDM2 in some breast cancers and these effects can be blocked by endocrine therapy fulvestrant and tamoxifen." (PMID 30689920, 2019). "For example, MDM4 and EGFR were enriched in glioblastoma, MYC and ERBB2 were enriched in breast cancer whereas MDM2 was enriched in both." (PMID 30674876, 2019). "Additionally, MDM4 is reported to be highly expressed in a significant percentage of human cancers, including 65% of retinoblastomas, 80% of adult pre-B lymphoblastic leukemia, 39% of head and neck squamous carcinomas, 19% of colon cancers, 19% of breast cancers, and 18% of lung cancers." (PMID 27742919, 2016). "Since MDM4 and MDM2 play well-characterized proliferative and prosurvival roles in breast cancer models, ERα-dependent upregulation of MDM4 and MDM2 surely enhances these processes." (PMID 26909605, 2016). "IR, similar to CEP-1347, has been shown to reduce the expression of MDM4 in breast cancer cells and sarcoma cells, but not yet in GBM or MM cells." (PMID 39273420, 2024). "Notably, we discovered novel miRNAs that target MDM4 and MDM2; this study enhances our understanding of the YAP1/Hippo pathway and the functions of miRNAs as novel therapeutic targets in breast cancer." (PMID 39345743, 2024). "Breast cancer metastasis is promoted by multiple factors including notable contributors such as C-X-C chemokine receptor 4 (CXCR4 also known as CD184), Mouse Double Minute 2 (MDM2), and Mouse Double Minute 4 (MDM4 also known as MDMX)." (PMID 39766093, 2024).
breast carcinoma (continued). "The addition of the SDF-1 chemokine to breast cancer cells upregulated MDM2 and MDM4." (PMID 39766093, 2024). "Antisense oligonucleotides-mediated MDM4 exon 6 skipping could prove useful as a therapeutic strategy for breast carcinoma, melanoma, and diffuse large B cell lymphoma (DLBCL), by decreasing MDM4 abundance and reducing the growth of these tumors." (PMID 34611130, 2021). "Since ERα-positive primary invasive breast carcinomas have elevated expression of MDM4 and MDM2 genes, we hypothesized that ERα mediates the upregulation of MDM4 and MDM2 in human breast cancer." (PMID 26909605, 2016). "This suggests direct signaling crosstalk and negative feedback loops between ERα and MDM4 expression in breast cancer cells." (PMID 26909605, 2016). "This is the first report to demonstrate that ERα and MDM4 exist in a protein complex with one another, and it is also the first report to demonstrate that endogenous ERα and MDM2 similarly complex with one another in breast cancer cells." (PMID 26909605, 2016). "Based on our observations from ChIP datamining studies, we postulate that ERα-dependent overexpression of MDM4 and MDM2 in human breast cancer is mediated, at least in part, by the ability of ERα to directly bind to and transcriptionally upregulate the MDM4 and MDM2 genes." (PMID 26909605, 2016). "In summary, a resequencing study of the MDM4 gene in 40 German breast cancer patients selected for family history did not reveal clearly pathogenic mutations although it uncovered two new unclassified variants at a low frequency." (PMID 18279506, 2008).
melanoma (65 papers, 2013 to 2026). A malignant, usually aggressive tumor composed of atypical, neoplastic melanocytes. "Taken together with the capture-HiC and CRISPRi already linking locus 4 to regulation of MDM4, these reinforce a potential role for MDM4 in melanoma risk." (PMID 39802764, 2024). "Our findings in this large population-based melanoma study now pave the way for further replication studies and for research to unveil the potential underlying mechanisms involving Mdm2/Mdm4 with melanoma development and outcomes." (PMID 37345045, 2023). "No other statistically significant associations were observed between the tested MDM2 and MDM4 variants and multiple melanoma or death in melanoma patients." (PMID 37345045, 2023). "We investigated SNP309, an a priori MDM4-rs4245739, and two coinherited variants, in a population-based cohort of 3663 primary incident melanomas." (PMID 37345045, 2023). "Per-allele and per-haplotype (MDM2_SNP309-SNP285; MDM4_rs4245739-rs1563828) odds ratios (OR) for multiple-melanoma were estimated with logistic regression models." (PMID 37345045, 2023). "Thus, it is plausible that these credible variants in MDM2 and MDM4 modify the risk for melanoma and survival in melanoma patients." (PMID 37345045, 2023). "Mutations in cancers other than HCC associated with a negative outcome for ICI treatment include inactivating mutations in JAK1/2 or beta-2-microglobulin in melanoma, MDM4 amplifications, or EGFR alterations in different stage IV tumors or STK11/LKB1 alterations in KRAS-mutant lung adenocarcinoma." (PMID 33353145, 2020). "We also searched for additional candidate functional MDM2/MDM4 variants in high LD with our tested single nucleotide polymorphisms (SNPs) that contribute to the genetic environment and create more or less favorable conditions in skin and/or distal tissues prone to melanoma metastases." (PMID 37345045, 2023). "The splicing factor SRSF3 drives the inclusion of exon 6 in MDM4, whereas ASO-mediated skipping of exon 6 effectively reduces MDM4 levels and significantly inhibits melanoma growth." (PMID 41510173, 2026). "It was present at higher levels than the MDM4-A isoform in all cases except 5 and 8, in which high levels of MDM4-FL were present, which has been previously characterized as the most abundant MDM4 isoform in melanomas." (PMID 39273363, 2024). "MDM4 is upregulated in the majority of melanoma cases and has been described as a “key therapeutic target in cutaneous melanoma”." (PMID 39273363, 2024). "Here, MDM4 transcripts, both alternative and canonical, are characterized in a pilot cohort of human melanoma specimens." (PMID 39273363, 2024). "We validated several such cis-regulatory interactions using CRISPR inhibition, providing evidence for known cancer driver genes MDM4 and CBL, as well as the SRY-box transcription factor SOX4, as likely melanoma risk genes." (PMID 39802764, 2024). "PRMT5 was found to specifically downregulate MDM4 protein levels in melanoma cell lines; multiple PRMT5 small molecule inhibitors are currently under evaluation in clinical trials." (PMID 39273363, 2024).